KDM4B (lysine demethylase 4B)
Description:
Histone demethylase that specifically demethylates 'Lys-9' of histone H3, thereby playing a role in histone code. Does not demethylate histone H3 'Lys-4', H3 'Lys-27', H3 'Lys-36' nor H4 'Lys-20'. Only able to demethylate trimethylated H3 'Lys-9', with a weaker activity than KDM4A, KDM4C and KDM4D. Demethylation of Lys residue generates formaldehyde and succinate. Plays a critical role in the development of the central nervous system (CNS).
Synonyms: JMJD2B; KIAA0876; TDRD14B; MRD65
Tractability: Small molecule: a structure with a bound ligand is known; a high-quality ligand is known. PROTAC: ubiquitination databases record sites on it; its protein half-life has been measured; a small molecule that binds it is known.
Target class: Lysine demethylase; Lysine-specific demethylase; Epigenetic regulator; Eraser
Gene: Protein-coding gene on chromosome 19 (4,969,107 to 5,153,611, forward strand). Ensembl gene ENSG00000127663.
Subcellular location: Nucleus
Subcellular location (Human Protein Atlas): Nucleoplasm; Cytosol
Pathways (Reactome):
Chromatin organization: HDMs demethylate histones
DNA Repair: Recruitment and ATM-mediated phosphorylation of repair and signaling proteins at DNA double strand breaks
Signal Transduction: Estrogen-dependent gene expression
Gene Ontology:
Molecular function: histone H3K36 demethylase activity; histone H3K9 demethylase activity; histone H3K9me2/H3K9me3 demethylase activity; histone demethylase activity
Biological process: brain development; chromatin remodeling
Cellular component: nucleoplasm; chromatin; nucleus
Genetic constraint (gnomAD): Loss-of-function variants: 29 observed, 106.46 expected, observed/expected ratio (o/e) 0.27, 90% interval 0.2 to 0.37. The upper end of that interval is the gene's LOEUF score, 0.37, which puts it in group 1 of 6, group 1 being the genes least tolerant of losing a copy. Missense variants: 1,182 observed, 1,495.1 expected, observed/expected ratio (o/e) 0.79, 90% interval 0.75 to 0.83. Synonymous variants: 717 observed, 643.32 expected, observed/expected ratio (o/e) 1.11, 90% interval 1.05 to 1.18.
Gene-disease validity (ClinGen):
ClinGen rates the evidence that KDM4B causes each of these diseases.
intellectual developmental disorder, autosomal dominant 65 (autosomal dominant): Strong.
Homologues: Orthologues: chimpanzee KDM4B (99% identical), macaque KDM4B (97% identical), pig KDM4B (89% identical), guinea pig KDM4B (83% identical), rat Kdm4b (81% identical), mouse Kdm4b (80% identical), dog KDM4B (79% identical), tropical clawed frog kdm4b (62% identical), zebrafish kdm4b (55% identical), Drosophila melanogaster Kdm5 (16% identical), Caenorhabditis elegans rbr-2 (14% identical). Paralogues in human: KDM4C (51% identical), KDM4A (47% identical), KDM4F (26% identical), KDM4D (26% identical), KDM4E (25% identical), KDM5A (20% identical), KDM5B (19% identical), KDM5C (19% identical), KDM5D (18% identical), JARID2 (9% identical).
Diseases named in the same sentence as KDM4B in open-access papers:
KDM4B is named in the same sentence as 105 diseases in open-access papers, as found by Europe PMC text mining. Sharing a sentence is not in itself a finding about the gene and the disease. The quoted sentences say what the papers report.
breast carcinoma (54 papers, 2011 to 2025). "Used in breast cancer, but combined with KDM4B inhibitors to sensitize PTEN-deficient tumors to apoptosis by inducing UPR and activating ATF4." (PMID 41301006, 2025). "In breast cancer, KDM4B has been implicated as an estrogen-regulated gene that acts as an ER co-factor in the promotion of luminal differentiation." (PMID 38317241, 2024). "E2 induction regulates the expression of KDM4B, which promotes ER+ breast cancer-associated gene expression." (PMID 35453496, 2022). "In breast cancer cells, HIF-1α upregulates the expression of KDM4B and further promotes the progression of breast cancer in association with ERα." (PMID 35186950, 2021). "Of note, KDM4B is associated with chromosomal instability in breast cancer; the overexpression of exogenous KDM4B leads to the loss of centromere-associated H3K9me3 and elevated chromosomal instability." (PMID 30683841, 2019). "KDM4B controls estrogen receptor signaling; hence, its reduced expression inhibits breast cancer progression." (PMID 40006021, 2025). "Inhibit KDM4B, upregulating UPR target ATF4 and triggering apoptosis in PTEN-deficient breast cancer cells." (PMID 41301006, 2025). "The histone demethylase KDM4B, a factor regulating these processes, plays important roles in estrogen receptor-mediated transcription and DNA repair in breast cancer." (PMID 39434131, 2024). "KDM4B interacts with the transcription factor GATA-3 in breast cancer cell lines and directly co-activates transcription factor activity in reporter-based experiments." (PMID 39000010, 2024). "KDM4B was degraded by a ubiquitin ligase SCFFbxo22 in the presence of selective estrogen receptor modulators (SERM) in breast cancer endocrine therapy." (PMID 39434131, 2024). "KDM4B plays an oncogenic role in breast cancer by upregulating estrogen receptor α (ERα) signaling, whereas KDM4B is transcriptionally targeted by ERα, forming a feed-forward regulatory loop." (PMID 39434131, 2024). "Using knockdown and overexpression approaches, a recent study has shown that KDM4B inhibits proliferation and metastasis in ER+ and ER- breast cancer cells, supporting a tumor suppressive role for KDM4B in both contexts." (PMID 38317241, 2024). "We propose that AR/GATA3-mediated induction of KDM4B facilitates maintenance of a luminal epithelial transcriptome in breast cancer cells and forms part of a tumor suppressive nexus regardless of ER status." (PMID 38317241, 2024). "Biallelic mutations causing immature stop codon(s) at the most N-terminal residues of KDM4B were created in two breast cancer cell lines: T-47D and MCF-7, and immunoblotting confirmed the deletion of the expression." (PMID 39434131, 2024). "Another study revealed that FBXO22‐induced degradation of KDM4B influences the activity of selective oestrogen receptor modulators (SERMs) in breast cancer." (PMID 39153212, 2024). "Previous findings on the importance of KDM4B on ERα signaling in breast cancer prompted us to further investigate its role in other functions." (PMID 39434131, 2024). "KDM4B is essential for ER-mediated transcription in breast cancer cell lines through direct interaction with ER and with its regulatory targets." (PMID 39000010, 2024). "For instance, KDM4B (JMJD2B) expression is significantly high in breast cancer compared with other cancers, suggesting its specific role in this cancer." (PMID 39434131, 2024). "KDM4B overexpression is reported to be predominant in both estrogen receptor–positive breast cancer and triple-negative breast cancer." (PMID 37067993, 2023). "Increased levels of KDM4A and KDM4B have been observed in ERα positive breast cancer cells, while TNBC cells showed an increased level of KDM4C." (PMID 36185256, 2022). "KDM4B overexpression promoted DNA damage in breast cancer cells which was significantly reduced upon pharmacological inhibition of KDM4B, by induction of apoptosis in triple negative breast cancers deficient in the tumor suppressor gene, PTEN." (PMID 34220955, 2021).
breast carcinoma (continued). "Relapse‐free survival (RFS) analysis data revealed a correlation between high KDM4B expression and good patient prognosis of the TCGA cases with breast cancer, THCA, cervical squamous cell carcinoma, esophageal adenocarcinoma, and UCEC (p < 0.05)." (PMID 34766154, 2021). "In breast cancer cell lines, KDM4B demethylation of repressive H3K9me3 marks within upstream regulatory ER promoter regions permits binding of GATA-3 to drive ER expression." (PMID 35186950, 2021). "In ER-positive breast cancer, the miR-491-5p, a tumor suppressor gene, directly targets the mRNA of KDM4B, and its overexpression inhibits breast cancer cell proliferation." (PMID 35186950, 2021). "KDM4B is highly expressed in estrogen receptor (ER) positive breast cancer and is a key regulatory gene." (PMID 35186950, 2021). "Studies have shown that KDM4B is highly expressed in breast cancer cells with positive ERα expression." (PMID 35186950, 2021). "KDM4B overexpression is usually found in various cancers including breast cancer, colorectal cancer, and gastric cancer." (PMID 33909202, 2021). "Lysine demethylase 4B (KDM4B) degradation in breast cancer cells is also mediated by FBXO22, leading to modulation of selective estrogen receptor modulator (SERM) activity and thus tamoxifen resistance in estrogen receptor (ER)-positive breast cancer cells." (PMID 35141150, 2021). "It is reported that KDM4B is associated with ERα (Estrogen receptor alpha)-dependent transcription and knockdown of KDM4B suppresses cell proliferation as well as tumor progression in breast cancer." (PMID 33909202, 2021). "The present study provides evidence of a co-operative role between the histone demethylase enzymes KDM3A and KDM4B in regulating ER-signalling in models of breast cancer." (PMID 31390833, 2019). "This is in contrast to the hypoxic induction of KDM4B in human and murine cells, as well as the estrogen-dependent induction of KDM4B in both breast cancer and murine mammary epithelium." (PMID 30759871, 2019). "In this case, breast cancer cells have a more differentiated phenotype, inducing expression of KDM4B and VDR while preventing expression of Wnt-signaling molecules." (PMID 30759871, 2019). "Although less well studied, there are indications that glucocorticoid receptors enhance the ESR1-dependent induction of KDM4B in breast cancer." (PMID 30759871, 2019). "The involvement of KDM4B in breast cancer has a clear contribution to the aggressive nature of the disease in ER+ subtypes." (PMID 30759871, 2019). "Since many of the estrogen-induced genes that regulate breast cancer proliferation and progression are also regulated by hypoxia (Cyclin D1, WISP2, etc.), KDM4B serves to integrate two known drivers of breast cancer progression." (PMID 30759871, 2019). "KDM4B is a master regulator in the estrogen-induced signaling cascade and its depletion attenuates breast cancer development in vitro and in vivo." (PMID 29880033, 2018). "KDM4B is oestrogen inducible and has been shown to promote oestrogen-stimulated breast cancer proliferation." (PMID 25145438, 2014). "KDM4A is down-regulated in bladder cancer, and KDM4A and KDM4B are up-regulated in breast cancer and peripheral nerve sheath tumours respectively." (PMID 25145438, 2014). "Breast cancer is associated with multiple histone demethylases, including KDM4A, KDM4B, and KDM4C." (PMID 40006021, 2025). "Combining inhibitors of the histone demethylase KDM4B, such as methylstat and PI3K/AKT inhibitors, upregulates the UPR downstream target ATF4, resulting in UPR activation and the apoptosis of PTEN-deficient breast cancer cells." (PMID 41301006, 2025). "KDM4B-knockout breast cancer cell lines were generated via CRISPR/Cas9-mediated gene editing." (PMID 39434131, 2024). "KDM4B was identified as an androgen-induced gene associated with the AR-GATA3 interaction in all breast cancer cell lines regardless of ER status." (PMID 38317241, 2024).
breast carcinoma (continued). "For example, KDM4A and KDM4D are co-overexpressed in basal breast cancer, while the KDM4A level is higher in infiltrating breast duct carcinoma (IBDC) than in breast fibroadenoma, and KDM4B is overexpressed in both estrogen receptor (ER)-positive breast cancer and triple-negative breast cancer." (PMID 37692513, 2023). "KDM4B regulates the cell cycle progression of breast cancer cells and is a direct target of ERα." (PMID 36185256, 2022). "However, KDM4B promotes the binding of DNA to topoisomerase 2.thereby improving the sensitivity of breast cancer cells to anthracyclines." (PMID 35186950, 2021). "One possible reason for this phenotype may be that estrogen receptors (ERs) regulate KDM4B in ER+ breast cancer, which makes KDM4B correlated to a subtype of cancer that is more effectively treated with Tamoxifen and other anti‐estrogens." (PMID 34766154, 2021). "Kaplan–Meier curves have improved outcomes for high KDM4B in breast cancer and uterine cancer." (PMID 34766154, 2021). "In breast cancer cells, the deletion of KDM4B not only reduces the transcription of WEE1, CCND1, and CCNA1, but also disrupts the estrogen-induced cell cycle G1-S phase transition, causing breast cancer cells to stall at the G2-M phase or G1-S phase." (PMID 35186950, 2021). "Therefore, KDM4B inhibitors cannot be used in conjunction with anthracyclines to treat breast cancer." (PMID 35186950, 2021). "A novel KDM4 inhibitor, NCDM-32B, has shown some utility in the treatment of a subset of aggressive breast cancers, in which it functions by disrupting several key pathways driving cell proliferation and transformation in breast cancer through inhibition of KDM4B expression." (PMID 35186950, 2021). "Histone demethylase KDM4B may enhance the LINE-1 retrotransposition efficacy, whereas depletion of KDM4B reduced it in breast cancer." (PMID 32850797, 2020). "Effectively targeting KDM4B in ER+ breast cancer patients could prevent Tamoxifen resistance by preventing re-expression through hypoxic signaling." (PMID 30759871, 2019). "Targeting KDM4B or its regulated pathways in ER+ breast cancer may enhance the actions of Selective Estrogen Receptor Modulators to prevent tumor growth and recurrence." (PMID 30759871, 2019). "The tumor suppressor miR-491–5p can bind KDM4B mRNA and slow ER-α+ breast cancer development." (PMID 30759871, 2019). "KDM4B is induced by estrogen, making it important for progression of ER+ breast cancers." (PMID 30759871, 2019). "Although whether these KDM4B inhibitors are able to reverse endocrine therapy resistance needs to be tested, we believe specific and potent KDM4B inhibitors hold a promise for overcoming endocrine therapy resistance to breast cancer and prostate cancer." (PMID 29342868, 2018). "unpublished data), suggesting ERα-positive breast cancer cells are more addicted to KDM4B." (PMID 29342868, 2018). "KDM4B has been found to mediate oestrogen stimulated cell proliferation of mammary cancer." (PMID 28536364, 2017). "Thus, KDM4B is recently considered a therapeutic target for breast cancer and other cancers." (PMID 39434131, 2024). "We validated that KDM4B protein expression was increased by DHT in ER+ and ER- breast cancer cell lines, and this increase was abrogated by AR knockdown." (PMID 38317241, 2024). "Various studies have shown that KDM4A/JMJD2A, KDM4B/JMJD2B, and/or KDM4C/JMJD2C are overexpressed in breast cancer, colorectal cancer, lung cancer, prostate cancer, and other tumors and are essential for the efficient growth of cancer cells." (PMID 39620228, 2024). "Conversely, KDM4B inhibition in breast cancer cells induced resistance to TOP2 inhibitors doxorubicin and etoposide, whereas the ectopic expression of KDM4B sensitized cells to etoposide." (PMID 39434131, 2024).
breast carcinoma (continued). "Nonetheless, three genes (CNTNAP2, EHF, KDM4B) were significantly upregulated by DHT in all four models of breast cancer and displayed enrichment of AR, GATA3, and H3K27ac ChIP-seq signals at associated genomic loci." (PMID 38317241, 2024). "Similar to KDM4B, KDM6A is also induced by ERα and forms an ERα transcription activator in breast cancer during hormone stimulation." (PMID 35453496, 2022). "The level of H3K9me3 in cells depended on histone lysine methyltransferases or the opposing demethylases, and various studies have shown that the demethylases KDM4A/JMJD2A, KDM4B/JMJD2B and/or KDM4C/JMJD2C are overexpressed in breast cancer." (PMID 36303253, 2022). "Identified as endogenous regulatory factors of KDM4B, several microRNAs, such as miRNA-491-5P, have been found to inhibit KDM4B expression by binding to the 3′ UTR of KDM4B mRNA, thereby inhibiting the proliferation of breast cancer and gastric cancer cells." (PMID 35186950, 2021). "The most advanced preclinical KDM4 inhibitor is JIB-04 which targets KDM4A, KDM4B, and KDM4E and can inhibit growth and reduce tumor burden in non-small cell lung cancer (NSCLC) and breast cancer in vitro and in vivo." (PMID 34220955, 2021). "Thus, KDM4B may function as a therapeutic target for both ER+ and ER- breast cancers." (PMID 30759871, 2019). "Finally, we show that depletion of both KDM3A and KDM4B has a greater inhibitory effect on ER activity and cell growth than knockdown of each individual enzyme, suggesting that targeting both enzymes represents a potentially efficacious therapeutic option for ER-driven breast cancer." (PMID 31390833, 2019). "Overall, the identification of a KDM3A/KDM4B co-regulatory axis that regulates FOXA1 and subsequent ER deposition on chromatin in breast cancer enhances the understanding of the mechanisms controlling ER-transcriptional activity." (PMID 31390833, 2019). "The KDM4 family members of JmjC enzymes, targeting di- and trimethylated H3K36 and H3K9, namely KDM4A, KDM4B and KDM4C are upregulated in breast cancer." (PMID 28536364, 2017). "Herein, we further demonstrate that KDM4B is an AR/GATA3 target gene in ER- and ER+ breast cancers, supporting the concept of AR co-operating with ER signaling to promote differentiation in ER+ disease and independently promoting differentiation in ER- disease." (PMID 38317241, 2024). "Other JmjC KDMs involved in breast cancer are KDM4A, KDM4B and, KDM4C." (PMID 36185256, 2022). "Moreover, histone demethylase KDM4B synergizes H3K4/H3K9 methylation and enhances hormonally responsive breast cancer." (PMID 33732698, 2021). "Similalry, KDM4B degradation is mediated by FBXO22 in breast cancer cells, resulting in regulation of selective estrogen receptor modulators (SERMs) activity, leading to modulation of tamoxifen resistance in ER-positive breast cancer cells." (PMID 32793396, 2020). "Importantly, in endocrine therapy-resistant breast cancer cells, the regulation of KDM4B by HIF-1α and ERα is intact and KDM4B is still required for G2/M phase progression." (PMID 29342868, 2018). "We next measured the levels of signature genes whose protein products could be pharmacologically targeted in breast cancer lines (AURKB, SUV39H1, SUV39H2 and KDM4B)." (PMID 27863398, 2016). "In clinical datasets, high expression of KDM4B, but not EHF (data not shown), was associated with better patient outcomes, although EHF is one of 142 genes comprising a gene signature of AR activity that is prognostic in ER+ breast cancer." (PMID 38317241, 2024). "In breast cancer, studies have revealed that KDM4B not only antagonizes H3K9 tri-methylation in peripheral heterochromatin and affects H3K4/H3K9 methylation but also plays a role in estrogen receptor α-regulated breast cancer development and mammary epithelial cells proliferation." (PMID 36755810, 2023).